TLR4 (toll like receptor 4)
Diseases named in the same sentence as TLR4 in open-access papers (continued):
Sharing a sentence is not in itself a finding about the gene and the disease.
acne (21 papers, 2012 to 2025). An inflammatory process of the sebaceous glands which is characterized by comedones, nodules, papules and/or pustules on the skin. "Using a subset of genotyping data of 982 acne cases and 846 controls extracted from our existing GWAS database, we found that out of all the gene variants in this systematic review, only TLR4 was significantly associated with acne presentation." (PMID 33849530, 2021). "We discovered 15 novel SNPs in the 3′ UTR region of the Toll-like Receptor 4 gene (TLR4) associated with acne presentation." (PMID 33849530, 2021). "An increase in the expression of both TLR2 and TLR4 was also demonstrated in keratinocytes and associated with the initial inflammatory process observed in acne lesions." (PMID 22448280, 2012). "Monocyte subpopulations expressing TLR2 and TLR4 circulating in the peripheral blood of patients with acne vulgaris appear to be indifferent to altered skin parameters: level of oiliness, hydration, and skin pigmentation (phototype, erythema)." (PMID 41010653, 2025). "In our research, we wanted to assess the level of expression of TLR2 and TLR4 on monocyte subpopulations in acne patients in the context of assessing the state of skin hydration, oiliness, pH, and erythema intensity using specialized probes." (PMID 41010653, 2025). "This study aimed to evaluate the percentage of monocyte subpopulations expressing TLR2 and TLR4, in relation to clinical data and skin function parameters, in patients with untreated acne vulgaris." (PMID 41010653, 2025). "The expression of TLR2 and TLR4 were significantly elevated in the acne lesions in the Finnish group." (PMID 25153527, 2014). "A higher percentage of non-classical monocytes TLR4+ in the blood is associated with a higher incidence of post-acne lesions." (PMID 41010653, 2025). "A total of 37 potential targets were predicted by network pharmacology, among which TNF, IL-1B, IL-6, ESR1, PPARG, NFκB1, STAT3, and TLR4 may be the key targets of GA in the treatment of acne." (PMID 38792208, 2024). "TLRs like TLR-2 can be found in macrophages and keratinocytes within the follicle and can contribute to acne pathogenesis; TLR-4 activity may also contribute to acne pathophysiology." (PMID 38534705, 2024). "The inflammatory response produced in acne is mediated through the detection of the C. acnes-pathogen-associated molecular patterns (PAMP), mainly peptidoglycan and lipoteichoic acid, by TLR2 and TLR4." (PMID 37232724, 2023). "The significant overexpression of pro-inflammatory markers such as Toll-like receptor-4 and interleukin-2 was observed both in the normal-appearing skin and inflammatory skin of acne patients with atrophic scars compared to acne patients without atrophic scars." (PMID 35806952, 2022). "None of the TLR4 variants (rs4986790 and rs4986791) investigated in the reviewed articles were found to be associated with acne risk." (PMID 33849530, 2021). "Furthermore, C. acnes can be recognized by pattern recognition receptors such as TLR2 and TLR4, which mount immune responses against the bacteria, thus influencing acne development." (PMID 33849530, 2021). "Significantly increased expression of TLR-4, IL-2, IL-10, and TIMP-2 and decreased MMP-9 havebeen demonstrated in patients with acne prone to scarring." (PMID 38398480, 2024). "It is suspected that, in the course of inflammatory acne, C. acnes activates cells by interactions with TLR2 and TLR4." (PMID 35329904, 2022). "The available microarrays from whole tissue biopsies of acne samples (GSE53795), histological analysis and in vitro experiments all suggested a role for the TLR1/2 and TLR4 pathways in the pathogenesis of acne." (PMID 29927962, 2018). "As P. acnes exposure leads to increases in TLR2 (as well as TLR4) expression in NHEK, and TLR2 expression was reported within acne lesions in situ, we choose to further investigate the role of this receptor in keratinocyte and sebaceous gland function." (PMID 24011352, 2013).
acne (continued). "In the group of patients with post-acne lesions, a statistically significantly higher percentage of non-classical monocytes expressing TLR4 was observed compared to patients without post-acne lesions (i.e., erythema, scars) (p = 0.009)." (PMID 41010653, 2025). "ATRA treatment decreased TLR2 levels in monocytes isolated from both healthy donors and acne patients following isotretinoin therapy, although TLR4 expression was not affected." (PMID 30319618, 2018). "Similarly, TLR2 and TLR4 as well as IL-8, IL-6, and TNF-α, were induced in acne lesions in the German group." (PMID 25153527, 2014). "However, we have demonstrated differences in the percentage of classical, intermediate, and non-classical monocyte subpopulations expressing TLR2 and TLR4 in patients with untreated acne vulgaris with selected skin parameters." (PMID 41010653, 2025). "Furthermore, a significantly higher percentage of non-classical TLR4+ monocytes was observed in the blood of acne patients with visible post-acne lesions compared to patients without post-acne cutaneous complications." (PMID 41010653, 2025). "Therefore, it has been hypothesized that Cutibacterium acnes stimulates cells during inflammatory acne by interacting with TLR2 and TLR4." (PMID 37687224, 2023). "Therefore, we hypothesize that the elevated PC and LPC identified in our study may be involved in the pathogenesis of acne by triggering TLR2 and TLR4-mediated signaling pathways to induce the production of inflammatory factors." (PMID 36120319, 2022). "Using a Venn diagram to visualize the up-regulated genes in the acne samples compared to healthy ones and in the TLR1/2- and TLR4-stimulated SZ95 sebocytes at 24 hours, a possible contribution of sebocytes with 92 of the 900 significantly altered transcripts in acne could be detected." (PMID 29927962, 2018).
experimental autoimmune encephalomyelitis (21 papers, 2012 to 2025). An autoimmune demyelinating disease of the central nervous system that is produced experimentally in animals by the injection of homogenized brain or spinal cord in Freund's adjuvant. "Toll-like receptor 4 (TLR4) plays a role in the pathogenesis of experimental autoimmune encephalomyelitis (EAE) by regulating CCL25/CCR9 expression in response to Th17 infiltration." (PMID 39199524, 2024). "A previous study reported that β-LAP inhibits the mRNA expression of TLR4 signaling molecules in experimental autoimmune encephalomyelitis mice." (PMID 26173397, 2015). "In addition, studies have shown that TLR4 antagonists can decrease the creation of pro-inflammatory factors and alleviate motor dysfunction in mouse models of experimental autoimmune encephalomyelitis." (PMID 38892278, 2024). "For example, TLR4 aggravates inflammation in experimental autoimmune encephalomyelitis (EAE) model." (PMID 30809253, 2018). "It has been previously reported that TLR-4, TLR-2, and adaptor MyD88 are directly involved in modulating the regulatory function of B cells in a murine model of experimental autoimmune encephalomyelitis (EAE)." (PMID 34867973, 2021). "The changes of TLR4 in CD4+ T cells from MS patients and experimental autoimmune encephalomyelitis (EAE) mice were tested." (PMID 31561751, 2019). "Specifically, Tlr4-mediated NF-κB activation drives the upregulation of proinflammatory cytokines (IL6, IL1β, and TNFα), which is consistent with its role in amplifying microglial reactivity in experimental autoimmune encephalomyelitis." (PMID 40563324, 2025). "Immunosuppressive properties of B cells, especially the production of IL-10 in experimental autoimmune encephalomyelitis (EAE) mice model is dependent on toll-like receptor-2 (TLR-2), toll-like receptor-4 (TLR-4)and myeloid differentiation primary response 88 (MyD88) signaling." (PMID 34867973, 2021).
liver failure (21 papers, 2012 to 2025). A liver disease characterized by the liver losing or has lost all of its function. "TLR4, a major signalling receptor of LPS, is closely linked to the pathogenesis and treatment of liver failure." (PMID 37644784, 2023). "Its influences on improving hepatic failure are achieved via the declined serum contents of alanine aminotransferase and aspartate aminotransferase in mice and the inhibition of toll-like receptor 4 (TLR4)/MAPK or TLR4/NF-κB in macrophages." (PMID 37069938, 2023). "Recently, some study reported that Toll-like receptor 4 (TLR4) is a therapeutic target for the prevention and treatment of liver failure." (PMID 33860064, 2021). "TAK‐242, TLR4 inhibitor ameliorates liver injury and systemic inflammation in rodent models of liver failure." (PMID 33336563, 2021). "Researchers showed that HMGB1 and TLR4 were reported to be closely related to inflammation and liver failure." (PMID 33959665, 2021). "The lipopolysaccharide (LPS)– toll-like receptor-4 (TLR4) pathway plays an important role in liver failure." (PMID 31942020, 2020). "Our previous study has confirmed that WYJDHY could modulate TLR4/NF-κB signaling during hepatic failure." (PMID 36339606, 2022). "Notably, the activation of the TLR4-NF-κB signal axis after liver resection played a pivotal role in the LPS-induced liver failure and the mortality of the mice." (PMID 30151394, 2018). "Therefore, treatment with JDHY granules improves liver function in an acute model of rat liver failure by downregulating TLR4 and IL-2 pathways." (PMID 28197212, 2017). "Studies have also demonstrated that TLR4 antogonists may reduce the extent of liver injury in acetaminophen and galactosamine induced liver failure models." (PMID 25244648, 2015). "Thus, targeting the TLR4-mediated NF-κB pathway may be a way to alleviate LPS/d-GalN—induced liver failure." (PMID 31077206, 2019). "In summary, this study demonstrated that ApoA5 had a protective effect against LPS/d-GalN-induced liver failure within a certain range by inhibiting TLR4-mediated NF-κB pathway, and ApoA5 might be a potential target for the prevention of FHF induced by LPS/d-GalN in mice." (PMID 31077206, 2019). "The inhibition of TLR4 signaling using a TLR4 inhibitor (TAK‐242) improved organ damage and systemic inflammation in a rat liver failure model." (PMID 41235399, 2025). "The first discovered TLR was toll-like receptor 4 (TLR 4) that mainly binds to lipopolysaccharide (LPS) and mediates tissue injury in liver failure." (PMID 40150093, 2025). "This agrees with data from rodent models which suggest that endotoxin activates cellular receptors including TLR4 on hepatic Kupffer cells to exacerbate APAP-induced liver injury and clinical liver failure." (PMID 25937432, 2015). "Furthermore, tectorigenin (TEC) was also one of the active ingredients of blueberries, which inhibited the expression of toll-like receptor-4 (TLR4) and the activation of the MAPK/NF-κB pathway to promote autophagy and protect liver failure." (PMID 35287671, 2022). "Combined with TEC improving liver failure by regulating autophagy pathway, and TEC regulated TLR4, NF-κB and MAPK pathway to inhibit the occurrence of inflammatory response, which all proved our view that TEC may improve NASH by regulating hepatocyte autophagy and pyroptosis." (PMID 35287671, 2022).
osteoporosis (21 papers, 2009 to 2026). A condition of reduced bone mass, with decreased cortical thickness and a decrease in the number and size of the trabeculae of cancellous bone (but normal chemical composition), resulting in increased fracture incidence. "TLR4 polymorphisms and aberrant expression of TLR4 have been associated with the clinical significance of osteoporosis in clinical practice." (PMID 38504994, 2024). "rs1057317 polymorphism in TLR4 3’-UTR inhibited the expression of TLR4 by miR-34a, which increased the susceptibility to osteoporosis." (PMID 38504994, 2024). "It has been shown that TLR4 deficiency attenuates the inflammatory response in the NF-κB pathway, thereby improving osteoporosis." (PMID 38504994, 2024). "Consistently, TLR4 Asp299Gly or TLR4 Thr399Ile polymorphisms have a major influence on adiposity, bone mineral density or osteoporosis status in elderly women." (PMID 38504994, 2024). "Four of them reported that the TLR4 polymorphisms were associated with the susceptibility to osteoporosis." (PMID 38504994, 2024). "miR-1906 mimic reduced bone loss of osteoporosis animal model by down-regulating the TLR4/MyD88/NF-kB pathway." (PMID 38504994, 2024). "This study demonstrated that dysregulation of circRNA-0134944 and TLR4 contributed to the severity of osteoporosis and the risk of osteoporotic fracture by modulating their specific signaling." (PMID 38504994, 2024). "It was reported that inhibiting TLR4/MyD88 signaling in osteoclast precursors effectively mitigates the progression of osteoporosis and subsequently bone loss." (PMID 38504994, 2024). "Osteoporosis was positively associated with the expression of circ_0134944 and TLR4 and negatively correlated to the expression of miR-630 in the blood and bone tissues samples." (PMID 38504994, 2024). "They found that although TLR4 was a candidate gene for osteoporosis in elderly women, the frequency of TLR4 Asp299Gly and TLR4 Thr399Ile allelic variants was low in postmenopausal women." (PMID 38504994, 2024). "The results revealed that osteoporosis was positively associated with the expression of circ_0134944 and TLR4 and negatively correlated to the expression of miR-630 in the blood and bone tissue samples." (PMID 38504994, 2024). "Since mounting clinical and experimental studies have investigated the potential role of TLR4 in osteoporosis, a better understanding of the biological function of TLR4 and its associated pathways on osteoporosis development is profound for the researchers." (PMID 38504994, 2024). "Clinical data showed that TLR4 polymorphisms and aberrant TLR4 expression have been associated with the clinical significance of osteoporosis." (PMID 38504994, 2024). "In agreement with previous studies, methionine can downregulate TLR4 and (or) NODs signaling in osteoclast precursors and thus decrease bone loss during osteoporosis in bovine mammary epithelial cells and improve the immune and antioxidant status." (PMID 35204204, 2022). "Also, in humans, both TLR4 polymorphisms and aberrant expression of TLR4 have been associated with the clinical significance of osteoporosis in clinical practice." (PMID 40001542, 2025). "This study showed that 8993C>T TLR4 polymorphisms in osteoporosis and control group were with statistically significant differences, including overrepresentation of heterozygous 8993CT genotype and mutated 8993T allele, and higher frequency of heterozygous 8993CT genotype and mutated 8993T allele." (PMID 38504994, 2024). "Among them, six included studies provided the clinical data from osteoporosis patients, 17 studies reported the molecular mechanisms underlying the role of TLR4 in osteoporosis, and seven studies provided the data of specific treatments-targeted TLR4 for osteoporosis." (PMID 38504994, 2024). "Since postmenopausal osteoporosis may be partially induced by low estrogen, estrogen-deficient may up-regulate the level of TLR4, thereby indicating the pivotal role of TLR4 in osteoporosis." (PMID 38504994, 2024).
osteoporosis (continued). "Studies reported the molecular mechanisms underlying TLR4-mediated osteoporosis." (PMID 38504994, 2024). "TLR4 is expressed on the surface of osteoclasts and osteoblasts, which regulates the immune response in patients with chronic inflammation, eventually causing the onset of osteoporosis." (PMID 38504994, 2024). "Furthermore, TLR4 Asp299Gly or TLR4 Thr399Ile polymorphisms were found to have a substantial impact on adiposity, bone mineral density, and osteoporosis status in elderly women." (PMID 38504994, 2024). "Since CD14 can initiate the signal transduction through TLR4 during the inflammatory response, abnormal TLR4 expression-associated osteoporosis may be partially mediated by the dysregulation of CD14." (PMID 38504994, 2024). "In fact, the innate immune receptor TLR4 has been implicated in the development of osteoporosis." (PMID 36747190, 2023). "In addition, in animal models of osteoporosis the pharmacological inhibition of its progression was also associated with an inhibition of TLR4 signaling." (PMID 29867550, 2018). "When intestinal microecology is disrupted, LPS enters blood circulation, activates the Toll-like receptor 4 (TLR4) signaling, and upregulates the expression of the NF-κB pathway, which in turn promotes the differentiation and activity of osteoclasts, leading to severe bone loss and osteoporosis." (PMID 40741168, 2025). "Mechanistically, dysregulation of osteoblasts and osteoclasts induced by abnormal expression of TLR4 is the main molecular mechanism underlying TLR4-mediated osteoporosis, which may be associated with the interactions between TLR4 and NF-κB pathway, proinflammatory effects, ncRNAs, and RUNX2." (PMID 38504994, 2024). "Although TLR4 being candidate gene for osteoporosis in the elderly women, the frequency of TLR4 Asp299Gly and TLR4 Thr399Ile allelic variants were low in postmenopausal women." (PMID 38504994, 2024). "There are six included studies (6/30, 20%) that provided the clinical outcomes of the expression of TLR4 in osteoporosis." (PMID 38504994, 2024). "A more recent study showed that the miR−137/KDM4A axis suppressed the osteogenic differentiation of human BMSCs (promoted osteoclast) and exacerbated osteoporosis by activating the TLR4/NF−κB pathway." (PMID 38504994, 2024). "E3 ubiquitin ligase CUL4A promoted osteoclast differentiation and osteoporosis by upregulating ZEB1 to repress miR-340-5p expression, causing HMGB1 upregulation and the TLR4 activation." (PMID 38504994, 2024). "HMGB-1 knockout suppressed ovariectomy-evoked activation of the TLR4/NF-κB signaling cascade, resulting in the alleviation of osteoporosis." (PMID 38504994, 2024). "MiR−137/KDM4A axis suppressed the osteogenic differentiation of human BMSCs and exacerbating osteoporosis by activating TLR4/NF−κB pathway." (PMID 38504994, 2024). "The present review highlights the important role of TLR4 in the clinical significance and the pathogenesis of osteoporosis from the aspects of inflammation and immunity." (PMID 38504994, 2024). "AEG-1 deletion improved bone remodeling in an osteoporosis animal model by inhibiting TLR4/MyD88/NF-κB pathway." (PMID 38504994, 2024). "Recently, increasing numbers of studies have demonstrated that Toll-like receptor 4 (TLR4, a receptor located on the surface of osteoclasts and osteoblasts) plays a pivotal role in the development of osteoporosis." (PMID 38504994, 2024). "The results of their study showed that high mobility group box 1 (HMGB-1) knockout suppressed ovariectomy-evoked activation of the TLR4/NF-κB signaling cascade, resulting in the alleviation of osteoporosis." (PMID 38504994, 2024). "Mechanistically, non-coding RNAs (i.e., circ_0134944 and miR-4485-3p) play an essential role in TLR4-mediated osteoporosis." (PMID 38504994, 2024). "This study is the latest comprehensive review focusing solely on the key role of TLR4 in clinical practice and the pathogenesis of osteoporosis." (PMID 38504994, 2024).